ENSG00000258667 (HIF1A antisense RNA 3)
Synonyms: HIFAL; HIF1A-AS3
Gene: Long non-coding RNA gene on chromosome 14 (61,678,402 to 61,751,163, reverse strand). Ensembl gene ENSG00000258667.
Gene Ontology:
Molecular function: ribosome binding
Diseases named in the same sentence as ENSG00000258667 in open-access papers:
ENSG00000258667 is named in the same sentence as 5 diseases in open-access papers, as found by Europe PMC text mining. Sharing a sentence is not in itself a finding about the gene and the disease.
ENSG00000258667 shares sentences with these, for which no sentence is quoted: breast carcinoma (7 papers); tumor (5); cancer (3); breast tumor (1); triple-negative breast carcinoma (1).